BECN1 (beclin 1)
Diseases named in the same sentence as BECN1 in open-access papers (continued):
Sharing a sentence is not in itself a finding about the gene and the disease.
ischemic stroke (21 papers, 2013 to 2025). A stroke disorder caused by obstruction of blood flow to the brain, due to thrombotic (local blood clot formation) or embolic (due to a blood clot or other material traveling from another site) event. "A recent study also demonstrated that EE promoted autophagy by increasing the expression of beclin-1 and enhancing the lysosomal activities of lysosomal-associated membrane protein 1, cathepsin B, and cathepsin D, which eventually boosted neurological function recovery following ischemic stroke." (PMID 34646128, 2021). "Lentiviral vectors carrying either Beclin-1 shRNA or a control sequence were injected into the peri-infarct region, followed by the induction of photothrombotic ischemic stroke using Rose Bengal one day later." (PMID 40894905, 2025). "By identifying critical thresholds and mechanisms through which Beclin-1 modulates cell fate, this work offers valuable insights into the development of targeted interventions aimed at enhancing neuroprotection in ischemic stroke." (PMID 40894905, 2025). "Beclin-1 plays a pivotal role in the interplay between autophagy and apoptosis in ischemic stroke, influencing both cell survival and death." (PMID 40894905, 2025). "To investigate the role of Beclin-1 in ischemic stroke pathology in vivo, we used a photothrombotic ischemic mouse model." (PMID 40894905, 2025). "This study explores the dual role of Beclin-1 in regulating autophagy and apoptosis during ischemic stroke, suggesting how its expression level and the severity of ischemic stress influence cell fate." (PMID 40894905, 2025). "In conclusion, our integrated experimental and modeling approach provides a deeper understanding of Beclin-1’s dual role in ischemic stroke, emphasizing the need for context-specific therapeutic strategies." (PMID 40894905, 2025). "They found that in contrast to miR-485, the expression of lncRNA SNHG3 was upregulated in ischemic stroke models, leading to increased levels of Beclin-1 and LC3-II/LC3-I ratio." (PMID 39021183, 2024). "The mechanisms are associated with suppressing TLR4/NF-κB pathway and NLRP3 inflammasome and enhancing LC3-II and Beclin-1 expressions after ischemic stroke." (PMID 34257822, 2021). "The results of the present study demonstrated that iMSC-sEV increased STAT3 activation during ischemic stroke, which was accompanied by a reduction in Beclin-1." (PMID 32698909, 2020). "Multiple reports demonstrate prolonged activation of autophagy proteins (e.g. LC3 and BECN1) and vacuoles in response to ischemic stroke/reperfusion in vivo, or oxygen-glucose deprivation (OGD) in vitro." (PMID 32208437, 2020). "On the other hand, our results regarding the effect of ischemic stroke on Beclin-1 expression are in agreement with the previous findings." (PMID 32273547, 2020). "Moreover, the ischemic stroke-weakened lysosomal capacity resulted in accumulation of autophagic substrates, as illustrated by the improved expressions of Beclin-1, LC3-II, insoluble p62, and ubiquitin." (PMID 34804431, 2021). "Furthermore, prolonged activation of autophagy proteins (e.g., LC3 and BECN1) and vacuoles in response to ischemic stroke/reperfusion in vivo, or oxygen-glucose deprivation (OGD) in vitro lead to significant cell death." (PMID 32208437, 2020). "SPK2 and Tat-SPK2 peptide promote neuronal survival through induction of autophagy, implying that SPK2 inducers, Tat-SPK2 peptide or agents acting on Beclin-1/autophagy pathway may provide candidate therapeutic agents against ischemic stroke." (PMID 28682313, 2017). "The coexpression of Mcl-1 with Beclin-1 might attenuate Beclin-1 dependent autophagy during ischemic stroke in rats." (PMID 25729215, 2015). "In addition, the coexpression of Mcl1 with beclin-1 may attenuate beclin-1-dependent autophagy during ischemic stroke in rats." (PMID 23688351, 2013).
ischemic stroke (continued). "Increased LC3 II/I ratio and Beclin-1 and a decrease in p62 are indications that up-regulated SNHG12 induced autophagy activation and reduced cellular injury during ischemic stroke." (PMID 39021183, 2024). "Markers of autophagy, including Beclin-1 and LC3B, were shown to be significantly elevated in ischemic stroke." (PMID 37446092, 2023). "Therefore, STAT3 may inhibit autophagy via a reduction in Beclin-1 in ischemic stroke." (PMID 32698909, 2020). "Furthermore, we showed that in the photothrombotic ischemic stroke mouse model - corresponding to the severe OGD conditions in vitro, shRNA-mediated knockdown of Beclin-1 reduced infarct size." (PMID 40894905, 2025). "Secondly, our focus on Beclin-1, while providing significant insights, may not account for the broader spectrum of molecular pathways involved in ischemic stroke, such as inflammation and oxidative stress." (PMID 40894905, 2025). "The results indicated that the levels of LC3 II/I ratio and Beclin-1 increased with time, whereas those of P62, p-mTOR/mTOR, and p-P70S6K/P70S6K were reduced in mouse brain after I/R and N2a cells after OGD/R, confirming the existence of autophagy in ischemic stroke." (PMID 33833132, 2021).
myocardial ischemia (20 papers, 2010 to 2025). A disorder of cardiac function caused by insufficient blood flow to the muscle tissue of the heart. "We used Western blotting detection to demonstrate that CQ10 noticeably increased the levels of the positively associated autophagy proteins beclin-1 and Atg5 at the same time points of acute myocardial ischemia-reperfusion injury (p < 0.05, n = 6)." (PMID 29348792, 2017). "In contrast, in a myocardial ischemia-reperfusion model, autophagy is elevated, and Becn1+/– mice have reduced autophagosome formation and myocardial injury." (PMID 38652543, 2024). "It is desirable to further test the regulation in other physio/pathological contexts, for example, the induction of Beclin 1 and autophagy during reperfusion phase after cardiac ischemia." (PMID 20454448, 2010). "The activation of ADORA2A promotes cell survival by inhibiting apoptosis and autophagy, thereby mitigating myocardial ischemia–reperfusion injury (MIRI), which may be associated with its capacity to activate the cAMP-PKA pathway and the Beclin-1-Bcl-2 complex." (PMID 40286230, 2025). "Potential translation to humans in the study is that Becn1 may act as an important intervention tool or potential drug for the patients with microvascular dysfunction post-myocardial ischemia reperfusion in the furture." (PMID 34732218, 2021). "Contrary to our findings, HBOT preconditioning (2.5ATA, 1hr, one time per day for 14days) could reduce Beclin-1 and increased mTOR expression resulting in the inhibition of exaggerated autophagy in rats with myocardial ischemia reperfusion injury." (PMID 33861726, 2021). "Then we examined the expression levels of autophagic markers in myocardial ischemia hearts and H9c2 cardiomyocytes, such as LC3-II/LC3-I ratio, Beclin 1 and p62." (PMID 29651246, 2018). "Meanwhile, LLC inhibited autophagy induced by myocardial ischemia injury, characterized by increased autophagic vacuoles, LC3-II/LC3-I ratio and the expression of Beclin 1, whereas decreased the expression of p62." (PMID 29651246, 2018). "The expressions of Beclin 1 and LC3-II/LC3-I ratio were upregulated, and the expression of p62 was downregulated in rat hearts and H9c2 cardiomyocytes subjected to myocardial ischemia injury when compared to control group, but it was markedly reversed by pretreatment of LLC." (PMID 29651246, 2018). "Autophagy induced by myocardial ischemia in mice is accompanied by activation of AMPK, whereas autophagy during reperfusion is accompanied by upregulation of the key protein Beclin 1 in the autophagy pathway, but not activation of AMPK." (PMID 33417139, 2022).
bladder cancer (19 papers, 2017 to 2025). "VCP also stabilized Beclin 1 and promoted autophagy in bladder cancer cells by downregulating ataxin-3." (PMID 37269429, 2023). "They found that the inhibition of PHLPP2 in bladder cancer cells promoted BECN1/Beclin1 degradation, attenuated autophagy, and promoted bladder cancer growth." (PMID 37737218, 2023). "Overall, our results showed that the circHIPK3/VCP/Beclin 1 axis plays an important role in regulating the proliferation and autophagy of bladder cancer cells." (PMID 37269429, 2023). "Co-IP confirmed that overexpression of circHIPK3 weakened the interaction of VCP and Beclin 1 in bladder cancer cells." (PMID 37269429, 2023). "In this study, JNK activation triggered autophagy of bladder cancer cell through dissociation of the Bcl-2/Bcl-xL–Beclin-1 complex following C-2 treatment." (PMID 31685029, 2019). "In our study, the autophagy process induced by C-2 is associated with autophagy factors such as ATG7, ATG5, ATG3, p62, LC3 and Beclin-1, therefore, the ability of C-2 to induce autophagy in bladder cancer cell lines was confirmed." (PMID 31685029, 2019). "However, some studies have found that Beclin-1 is expressed at low levels in bladder cancer, salivary gland adenoid cystic carcinoma, and pancreatic ductal adenocarcinoma and that patients with low Beclin-1 expression have shorter survival times." (PMID 32547955, 2020). "Similarly, the inhibition of autophagy, by using the specific inhibitor bafilomycin A or Beclin 1 knock-down enhanced the capsaicin-induced cell death in bladder cancer cells." (PMID 30695053, 2019). "Similarly, autophagy-related LC3BI/II and Beclin 1 expressions were abolished by NAC in ACT-treated bladder cancer cells." (PMID 29348843, 2017).
bladder cancer (continued). "However, the role of VCP in cancer is still unclear, and whether VCP can promote autophagy levels by stabilizing Beclin 1 in bladder cancer is also unclear." (PMID 37269429, 2023). "In prostate and bladder cancers, HMGB1 released during chemotherapy boosts autophagy via Beclin-1, reducing drug toxicity and aiding tumor survival." (PMID 40969278, 2025). "However, Beclin-1 only has a trend for bladder cancer survival, not significant association." (PMID 31772653, 2019). "Furthermore, we demonstrated that the HT1197 bladder cancer cell line is resistant to obatoclax treatment when autophagy is complete; however, when we used obatoclax in combination with paclitaxel, apoptotic cell death was induced after the autophagy blockade and beclin-1 cleavage." (PMID 30563080, 2018).
heart failure (19 papers, 2018 to 2026). Inability of the heart to pump blood at an adequate rate to meet tissue metabolic requirements. "The HSPB6S10F mice showed reduced autophagy due to impaired interaction between mutated HSPB6 and Beclin-1, which in turn led to heart failure and early death." (PMID 37623365, 2023). "In the TAC model, on the one hand, the expression of Becn1 was shown to control pro-hypertrophic and profibrotic responses in the heart, suggesting that autophagy enhances pressure-overload-induced heart failure." (PMID 37623365, 2023). "According to the results from our study, the combination of Met with GS significantly prevented the increase in the ratio of LC3-II to LC3-I in heart failure mice, reduced the expression of the autophagy markers Beclin 1 and Atg5, and reversed the decrease in the p62 protein." (PMID 39141645, 2024). "In addition, Tat-Beclin 1 peptide, derived from a region of the autophagy protein, beclin 1, can promote autophagy/mitophagy and improve mitochondrial function in heart failure animal models." (PMID 32435642, 2020). "Repressing the mitophagy exacerbates mitochondrial dysfunction and TAC-induced heart failure, whereas injection of a peptide of autophagy inducer (Beclin-1) mitigates mitochondrial dysfunction and TAC-induced heart failure at least partially by restoration of autophagy and mitophagy." (PMID 32085438, 2020).
Hyperglycemia (19 papers, 2012 to 2025). An increased concentration of glucose in the blood. "Since LC3 II/LC3 I and Beclin-1 are the biomarkers for the induction of autophagy, it is suggested that hyperglycemia induces renal autophagy." (PMID 38800022, 2024). "Of note, the level of Beclin-1 decreased dramatically, even lower than the basal level, after prolonged hyperglycaemia over 8 weeks." (PMID 35883796, 2022). "The inhibition of TLR4 expression improves bone metabolism, promotes ALP and bone mineralization, and reduces hyperglycemia-induced osteoblast apoptosis, levels of inflammatory factors, and the expression of Beclin 1 and LC3II/LC-I." (PMID 33995003, 2021). "Inhibition of calpain also restored the levels of autophagy in both iPSC-ECs and HAECs exposed to hyperglycemia marked by higher levels of BECLIN 1 and LC3-II normalized against GAPDH and increased formation of autophagosomes." (PMID 30799273, 2019). "LC3II/LC3I ratio was significantly decreased due to acute hyperglycemia, however, other autophagy-related proteins such as Beclin-1, total and Triton X-100-insoluble SQSTM1/p62, phospho-ULK1 (Ser555), ATG7 and BNIP3 were unchanged in AHG group." (PMID 26581389, 2015). "In STZ-treated rats, which present hyperglycemia and low insulin, autophagy proteins (LC3, ATG5, ATG12, and BECN1) were significantly elevated in the gastrocnemius muscle, which contributed to the increase of p-FOXO3a and the subsequent repression of mTOR." (PMID 37876013, 2023). "Hyperglycemia inhibits Jun N-terminal kinase (JNK) signaling and enhances the interaction between Beclin-1 and Beclin-2 resulting in autophagy inhibition." (PMID 32455017, 2020). "In conditions of hyperglycemia or deprivation of amino acids and serum, autophagy was activated by the IKK/NF-κB pathway coupled to beclin-1 gene expression." (PMID 30696869, 2019). "Our results showed that autophagy was significantly activated in response to hyperglycemia, and enforced expression of H19 in diabetic rats decreased the number of autophagosomes and reduced the expression of LC3-II, BECN1 and ATG7." (PMID 27903964, 2017). "In contrast, in animals with glucose infusion hyperglycemia, which present hyperinsulinemia, autophagy markers, including LC3-II/I, ATG7, and BECN1 decreased in gastrocnemius muscle, indicating that insulin in the lack of insulin resistance can suppress autophagy in skeletal muscle." (PMID 37876013, 2023). "Measurement of autophagic levels by immunoblotting revealed lower levels of both BECLIN 1 and LC3-II in iPSC-ECs and HAECs exposed to hyperglycemia, further supported by reduced presence of autophagosomes compared with iPSC-ECs in normoglycemic condition, demonstrating an impairment in autophagy." (PMID 30799273, 2019). "In spite of a decreased LC3II/LC3I ratio, other markers of autophagy, such as ATG7, ULK1 phopsphorylation, Beclin 1 and SQSTM1/p62, were not modulated by acute hyperglycemia." (PMID 26581389, 2015).
atherosclerosis (18 papers, 2013 to 2025). A disease characterized by the build-up of fatty material and calcium deposition in the arterial wall resulting in partial or complete occlusion of the arterial lumen. "Nonetheless, it is important to note that the upregulation of miR-129-5p has also been implicated in the development of atherosclerosis by impairing the protective effects of endothelial cell autophagy through miR-129-5p-mediated Beclin-1 suppression." (PMID 37568412, 2023). "The anti-apoptosis effects of TXL on atherosclerosis was related to the improvement of autophagy via Beclin-1." (PMID 34248627, 2021). "Beclin-1/Atg6 heterozygous deficient mice, which are only haploinsufficient for autophagy, did not develop worse atherosclerosis than Apoe-/- littermates." (PMID 26847458, 2016). "Interleukin-6 (IL-6), a key pro-inflammatory cytokine elevated in atherosclerosis, activates JAK2 signaling and induces the phosphorylation of Beclin 1 (BECN1), a critical protein involved in the initiation of autophagy." (PMID 40244103, 2025).